SOX2 (SRY-box transcription factor 2)
Diseases named in the same sentence as SOX2 in open-access papers (continued):
Sharing a sentence is not in itself a finding about the gene and the disease.
neuroblastoma (27 papers, 2013 to 2025). Neuroblastoma (NB) is the most common solid, extracranial childhood tumor. "It has been shown that hypoxia is able to maintain the stem-like phenotypes in neuroblastomas and activate signaling pathways that are associated with undifferentiated phenotypes of normal stem cells, including sex determining region Y box 2 (Sox2), Oct-4, and Notch-1 signaling." (PMID 24693428, 2014). "Similar to human neural progenitor cells, human neuroblastoma cells are characterized by a high content of SOX2+ cells and co-expression of the β-III-tubulin and GFAP." (PMID 37047534, 2023). "While all cell lines were negative for MYCN amplification (two copies of gene in the genome), HTR3A protein expression was associated with expression of major drivers of aggressive neuroblastomas, N-MYC and c-MYC44,45, or one of the core stemness factors SOX2." (PMID 35614045, 2022). "In neuroblastoma, Sox2 overexpression was shown to enhance tumorigenesis, while inhibiting tumor cell differentiation." (PMID 33788424, 2021). "Dual therapy of retinoic acid and proteasome inhibitor induced apoptosis, decreased stem cell markers such as Nestin, Sox2 as well as Oct4, and impaired neurosphere formation in neuroblastoma cell lines." (PMID 31191243, 2019). "Similar to BM-MSCs, NB-MSCs showed marked expression of stemness markers (Sox2, Nanog, Oct3/4), neuroblastoma stemness marker (CD117), and the oligodendrocyte marker O4." (PMID 30482160, 2018). "Study also confirmed that MYCN and SOX2 were involved in the mechanism of neuroblastoma formation." (PMID 32857725, 2020). "The presence of both Tuji+ve and SOX2+ve cells is in line with clinical observations of tumour heterogeneity including stem-cell like populations in neuroblastoma that are thought to be responsible for therapeutic resistance and demonstrates the greater physiological relevance of perfused cultures." (PMID 28842598, 2017). "Furthermore, the hydrogel environment appeared to modulate expression of neural markers, CD133 and SOX2, which are also considered markers of “stemness” of tumour initiating cells, and are important prognostic markers of neuroblastoma progression and development." (PMID 32321995, 2020). "We therefor believe that sutent may play anti-self-renewal and anti-malignancy roles in neuroblastoma tumorspheres by inhibiting the protein expression of the stemness-maintenance drivers, SOX2 and PDGFRβ as well as the malignant, proliferative markers MYCN and survivin." (PMID 29298329, 2018). "In contrast, the expression of PROM1, SOX2, and NESTIN, three neuroblastoma stem cell markers, exhibited a notable increase in all iLIN28B samples compared to their corresponding CTRLs." (PMID 40679030, 2025). "Gene expression analysis of NSs by quantitative polymerase chain reaction (qPCR) of β-catenin, NeuroD1, SOX2, Nestin, β-tubulin 3, and DCX genes was compared between each group and the SHSY-5Y neuroblastoma (positive control for neuronal cells)." (PMID 36835256, 2023). "After irradiation with the THz pulses for 30 min, more than 66% of the neuroblastoma cells maintained their SOX2 expression, and no mature MAP2b+ neurons were observed." (PMID 37047534, 2023).
neuroblastoma (continued). "The increased catalytic activity of ADAM10 and Sox2 expression is in conjunction with gamma (γ)-secretase inhibition, suggesting an antagonistic relationship between Sox2 and γ-secretase activity, demonstrated in both HEX 293 and human neuroblastoma SH-SY5Y cells lines." (PMID 39336125, 2024). "In order to validate the findings from the fibroblast cells, we also examined the effect of melatonin treatment in human neuroblastoma SH-SY5Y cells, demonstrating that melatonin could increase the expression of Sox2 significantly in a concentration-dependent manner." (PMID 39336125, 2024). "A reduced expression level of Oct4, SOX2 and NESTIN was found, whereas TrkA, TH, MAP2 and TUJ1 was increased in USP3-silenced cells, suggesting that USP3 downregulation might impair self-renewal capacity in neuroblastoma." (PMID 37170124, 2023). "Similarly, SOX2 is another stemness gene highly expressed in cancer stem cells with an intimate involvement in GBM progression and metastasis as well as promotion of tumorigenicity in Neuroblastoma (NB)." (PMID 32092088, 2020). "SK-N-BE neuroblastoma cells were shown to form CD133+ tumorspheres, unlike SH-SY5Y cells, hence we have first sorted CD133− and CD133+ SK-N-BE cells and showed that expression of CD133, ELK-1, SOX2, NANOG, and POU5F1 were all significantly more in CD133+ cells than in CD133− cells." (PMID 33672811, 2021).
oral squamous cell carcinoma (27 papers, 2013 to 2026). "This study aims to determine association of SOX2 and podoplanin expression in the progression of oral squamous cell carcinomas and to elucidate the association between two proteins." (PMID 31508790, 2019). "The study shows that there is an association between SOX2 and podoplanin during the development and progression of oral squamous cell carcinomas." (PMID 31508790, 2019). "This is the first publication, to our knowledge, regarding this topic in the field of oral squamous cell carcinoma showing a group of patients with poorer overall survival by representing a distinct expression pattern of SOX2 and SOX9." (PMID 39180200, 2025). "The protein biomarker SOX2 is found in embryonic cancer stem cells (CSCs), with well-established implications for oral potential malignant disorders (OPMDs) and oral squamous cell carcinoma (OSCC)." (PMID 38352102, 2024). "The pluripotency transcription factor SOX2 is frequently overexpressed in cancers, including oral squamous cell carcinoma (OSCC), thereby providing a link between malignancy and stemness." (PMID 31640140, 2019). "Few studies have analyzed the expression of SOX2 and podoplanin in the progression of oral squamous cell carcinomas." (PMID 31508790, 2019). "The immunohistochemical expression of SOX2 and podoplanin were evaluated in 60 cases of primary oral squamous cell carcinomas." (PMID 31508790, 2019). "A study evaluating the expression of SOX2 in oral squamous cell carcinomas has shown that a tumor with a high nuclear expression of SOX2 had longer disease-free survival period following postoperative radiotherapy." (PMID 31508790, 2019). "For example, SOX2, OCT4, and NANOG were found to be overexpressed in several cancers, including breast, prostate, and oral squamous cell carcinoma, and their expression levels were associated with tumor transformation, tumourigenicity, and tumor metastasis." (PMID 29868483, 2018). "High SOX2 expression is detected in various oral squamous cell carcinomas (e.g., oral cavity and tongue); such expression is thought to be activated through gene copy number gain and is associated with poor prognosis." (PMID 24410919, 2014). "SOX2 regulates the response to chemoradiotherapy and tumorigenesis of oral squamous cell carcinoma." (PMID 37636389, 2023). "–15 This study aimed to correlate the combined expression of SOX2 and podoplanin with the clinicopathological features of oral squamous cell carcinoma, and thereby to determine their influence on the progression and clinical outcome of oral squamous cell carcinomas." (PMID 31508790, 2019). "The overexpression of SOX2 has been reported in 60% to 88% of oral squamous cell carcinoma cases." (PMID 31508790, 2019). "SOX2 is also frequently amplified and overexpressed in oral squamous cell carcinoma." (PMID 23718828, 2013). "In oral squamous cell carcinoma (OSCC), higher SOX2 expression is frequently observed in well-differentiated tumours, suggesting that SOX2 may be associated with a more differentiated epithelial phenotype and correspondingly lower rates of lymph node metastasis, as well as better clinical outcomes." (PMID 41561279, 2025). "Expression of LINC-ROR has been reported to be upregulated in undifferentiated oral squamous cell carcinoma and correlated with the overexpression of KLF4, C-MYC, OCT4, and SOX2." (PMID 33745265, 2021). "A recent publication reported that suppressing Let-7 increased Oct4 and Sox2 expression in CSC-like oral squamous cell carcinoma (OSCC) by targeting ARID3B and HMGA2, which directly interact with Oct4 and Sox2." (PMID 26983719, 2016). "CSCs in oral squamous cell carcinomas show an increased expression of CD44, Oct4, Nanog, and Sox2, which may be utilized as candidate therapeutic targets." (PMID 37958336, 2023). "The role of SOX2 in oral squamous cell carcinoma is not widely explored and is still not precisely understood." (PMID 31508790, 2019).
oral squamous cell carcinoma (continued). "In the present study, we demonstrated that ALDH+ human oral squamous cell carcinoma (OSCC) cells are characterized by upregulated expression of the pluripotency transcription factors OCT4, Nanog and Sox2, as well as exhibit enhanced cancer stemness, as demonstrated by enhanced tumorsphere formation." (PMID 30143678, 2018). "Similarly, a recent study clearly demonstrated that inhibition of NF-kB reduces the expression of stem cell transcription factors SOX-2, NANOG, and Oct-4 in CSCs that present overexpression in several cancers, including breast, prostate, and oral squamous cell carcinoma." (PMID 33218351, 2020). "Additionally, it explores impacts on stem cell genes, SRY-box transcription factor 2 (SOX2), octamer-binding transcription factor 4 (OCT4), and Nanog homeobox (NANOG), linking tobacco to cancer stem cell proliferation and metastasis (e.g., oral squamous cell carcinoma)." (PMID 41782786, 2026).
endometrial cancer (24 papers, 2010 to 2025). Primary or metastatic malignant neoplasm involving the endometrium (mucous membrane that lines the endometrial cavity). "An aldehyde dehydrogenase (ALDH)-1high cancer stem-like cell subpopulation isolated from other endometrial cancer cell lines also showed increased expression of EMT-associated genes like SNAI1 as well as pluripotency markers Sox2 and Nanog." (PMID 35328833, 2022). "It is possible that SOX2 also participate in the early carcinogenesis of endometrial cancer via interaction with other risk factors." (PMID 20814443, 2010). "In summary, hypermethylation in association with reduced expression of SOX2 was demonstrated in endometrial carcinoma." (PMID 20814443, 2010). "The expression of other genes related to stemness, such as OCT4 and SOX2, was found to be similar in both types of endometrial cancer." (PMID 40433700, 2025). "According to the qRT-PCR and western blot results, we found that the expression of Sox2 in endometrial cancer tissues was higher than that in normal endometrial tissues." (PMID 36869031, 2023). "Our results showed that the expression of Sox2 was significantly increased in endometrial cancer tissues and ECSCs and was negatively correlated with the expression of miR-136." (PMID 36869031, 2023). "The PVT1/miR-136/Sox2/UPF1 axis provides a promising novel approach for the treatment of endometrial cancer, especially refractory endometrial cancer." (PMID 36869031, 2023). "Recent studies revealed that IGF2BP1 bound to the 3’UTR m6A site of SOX2 mRNA and inhibited the degradation of SOX2 mRNA, which in turn led to the proliferation and metastasis of endometrial cancer cells." (PMID 35945641, 2022). "Further, CD133/CD44+ cells isolated from endometrial cancers expressed the pluripotency markers Myc, Sox-2, Nanog and Oct4 as well as other stemness-related genes such as Nestin and showed enhanced clonogenic ability and sphere formation." (PMID 35328833, 2022). "IGF2BP1 recognizes the m6A site on PEG10 and SOX2 mRNAs and increases the expression of these mRNAs by enhancing their stability, promoting the malignant progression of endometrial cancer." (PMID 35945641, 2022). "Further, miR-15a-5p-mediated inhibition of Wnt/β-Catenin signaling suppressed cell proliferation and stemness of endometrial cancer cells, as it regulates the expression of various stemness genes like Oct-4, Sox2 and Nanog." (PMID 35328833, 2022). "Furthermore, high SOX2 accompanied by low p21 expressions in the patients of advanced endometrial cancer were associated with the most unfavorable outcomes, which indicated that the expression of SOX2 and p21 may be a useful biomarker for disease prognosis in endometrial cancer patients." (PMID 34731191, 2021). "As the results shown in Cancer Science by Kaoru Yamawaki in 2017, SOX2 expression is correlated with histological grade and poor prognosis in endometrial cancer." (PMID 34731191, 2021). "As TGF-β inhibits SOX2 signaling in iPSC31, we measured the effect of TGF-β stimulation on SOX2 expression in endometrial cancer cells." (PMID 30510261, 2018). "To identify SOX2-positive endometrial cancer cells for further oncogenic analysis, we checked SOX2 expression in Ishikawa (ESR1-positive) and its descendant Ishikawa-02 (ESR1-negative) cells." (PMID 30510261, 2018). "We performed an immunohistochemistry assay to detect SOX2 expression in normal endometrial tissues and endometrial carcinoma." (PMID 30510261, 2018). "Taken together, we found that SOX2 is highly expressed in endometrial carcinoma, in which SOX2 crosstalks with cytokine signaling to promote cell proliferation and migration, thereby predicting poor survival." (PMID 30510261, 2018). "Here, we observed that SOX2 contributes to cell cycle progression, thus increasing cell proliferation in endometrial carcinoma cells." (PMID 30510261, 2018). "Immunohistochemistry analysis revealed that SOX2 expression correlated with lymph node infiltration of endometrial carcinoma." (PMID 30510261, 2018).
endometrial cancer (continued). "Our data indicate that cytokine-mediated SOX2–EGFR signaling promotes malignancy in endometrial carcinoma." (PMID 30510261, 2018). "To study the effect of TGF-β stimulation on SOX2-mediated growth in endometrial carcinoma cells, we treated Ishikawa and Ishikawa-02 (SOX2-high) cells with TGF-β and performed a clonogenic analysis." (PMID 30510261, 2018). "To study the role of SOX2–EGFR signaling in the migration of endometrial carcinoma, we performed cell tracking analysis on Ishikawa-02 (SOX2-high) and 02-S (SOX2-low) cells." (PMID 30510261, 2018). "Compared with normal endometrial tissues, we found that SOX2 was highly expressed in endometrial carcinoma." (PMID 30510261, 2018). "All these data indicate that SOX2–EGFR signaling promotes the migration of endometrial carcinoma cells." (PMID 30510261, 2018). "We found that SOX2-high endometrial carcinoma cells possessed a higher colony-forming ability than their SOX2-low counterparts, and knockdown of SOX2 attenuated the colony-forming ability." (PMID 30510261, 2018). "Our findings suggest that the SOX2–EGFR signaling is hijacked in endometrial carcinoma to promote cell cycle progression." (PMID 30510261, 2018). "Our findings support that cytokine-induced stem cell factor SOX2 possesses oncogenic properties, with the potential to serve as a prognostic biomarker in endometrial carcinoma." (PMID 30510261, 2018). "It is currently unclear why SOX2, a transcription factor important for self-renewal and pluripotency of stem cells, is downregulated in endometrial cancers." (PMID 20814443, 2010). "Here, our results suggest more frequent hypermethylation events, at least in the investigated CpG islands of SOX2 gene, in endometrial cancer samples than in normal endometrium." (PMID 20814443, 2010). "Our observation that SOX2 was downregulated in endometrial cancer actually concurs with the mentioned analysis." (PMID 20814443, 2010). "By methylation-specific polymerase chain reaction (MS-PCR), the methylation status of SOX2 promoter region in 72 endometrial carcinomas and 12 normal endometrial samples was examined." (PMID 20814443, 2010). "Hypermethylation of the SOX2 promoter was observed in 37.5% (27/72) of endometrial carcinomas, and 8.3% (1/12) of normal endometrial tissues." (PMID 20814443, 2010). "Endometrial CSCs isolated from endometrial cancer expressing stemness markers, including SOX2, OCT4, MYC, ABCG2, NES, and NANOG, have been demonstrated to show greater expansion potential and colony-forming capabilities, as well as to express self-renewal genes." (PMID 38539419, 2024). "Furthermore, SMOC2 silencing resulted in the diminished clonogenic potential of endometrial cancer and reduced the expression of stemness-related genes, including SOX2, OCT4, and NANOG." (PMID 38539419, 2024). "Chen G et.al found that demethylases ALKBH5 could promote pluripotent stem cell transcription factor SOX2 transcription via removing its mRNA methylation, thus sustaining the stemness and tumorigenicity potential of endometrial cancer stem cells." (PMID 37283789, 2023). "The elevation of Sox2 is positively correlated with poor prognosis in endometrial cancer." (PMID 36869031, 2023). "Moreover, EGF stimulation induced SOX2 expression and promoted migration in endometrial cancer cells." (PMID 30510261, 2018). "We found that SOX2-high endometrial cancer cells migrate more than their SOX2-low counterparts." (PMID 30510261, 2018). "Since TGFBR2 is partially silencing mutated in Ishikawa and Ishikawa-02 cells, instead of adopting short-term TGF-β treatment for 24 hours used in the conventional invasion assay, we measured long-term TGF-β effect for 10 days on endometrial cancer cell growth and SOX2 expression." (PMID 30510261, 2018). "Therefore, more frequent hypermethylation in SOX2 promoter in endometrial cancers than in normal endometrial tissues was observed (P = .0472, chi-square test)." (PMID 20814443, 2010).